BTBD9 (BTB domain containing 9)
Synonyms: KIAA1880; dJ322I12.1
Tractability: PROTAC: ubiquitination databases record sites on it.
Gene: Protein-coding gene on chromosome 6 (38,168,451 to 38,640,172, reverse strand). Ensembl gene ENSG00000183826.
Subcellular location (Human Protein Atlas): Nucleoplasm
Gene Ontology:
Molecular function: protein binding; fumarylacetoacetase activity
Biological process: adult locomotory behavior; circadian behavior; modulation of chemical synaptic transmission
Cellular component: cytoplasm; glutamatergic synapse
Genetic constraint (gnomAD): Loss-of-function variants: 44 observed, 58.97 expected, observed/expected ratio (o/e) 0.75, 90% interval 0.58 to 0.96. The upper end of that interval is the gene's LOEUF score, 0.96, which puts it in group 4 of 6, group 1 being the genes least tolerant of losing a copy. Missense variants: 553 observed, 738.34 expected, observed/expected ratio (o/e) 0.75, 90% interval 0.7 to 0.8. Synonymous variants: 246 observed, 271.73 expected, observed/expected ratio (o/e) 0.91, 90% interval 0.81 to 1.01.
Homologues: Orthologues: chimpanzee BTBD9 (100% identical), macaque BTBD9 (99% identical), rabbit BTBD9 (98% identical), dog BTBD9 (98% identical), pig BTBD9 (98% identical), guinea pig BTBD9 (96% identical), mouse Btbd9 (96% identical), rat Btbd9 (96% identical), tropical clawed frog btbd9 (83% identical), zebrafish btbd9 (70% identical), Drosophila melanogaster BTBD9 (50% identical), Caenorhabditis elegans hpo-9 (38% identical), and 2 more. Paralogues in human: BTBD6 (19% identical), BTBD2 (17% identical), BTBD1 (17% identical), BTBD3 (17% identical), ABTB3 (16% identical), ABTB2 (15% identical), ABTB1 (12% identical), KBTBD4 (11% identical), KLHL11 (10% identical), SPOP (9% identical), SPOPL (8% identical).
Diseases named in the same sentence as BTBD9 in open-access papers:
BTBD9 is named in the same sentence as 25 diseases in open-access papers, as found by Europe PMC text mining. Sharing a sentence is not in itself a finding about the gene and the disease. The quoted sentences say what the papers report.
restless legs syndrome (18 papers, 2012 to 2025). A condition that occurs while resting or lying in bed; it is characterized by an irresistible urgency to move the legs to obtain relief from a strange and uncomfortable sensation in the legs. "BTBD9 has been identified as one of the most common genetic risk factors for restless leg syndrome (RLS)." (PMID 41009966, 2025). "Two of the ten new sleep duration signals, rs113851554 in MEIS1 (P = 2 × 10−25) and rs9369062 in BTBD9 (P = 2 × 10−10), have previously been associated with restless legs syndrome." (PMID 30952852, 2019). "Genome-wide association studies have linked mutations in three human genes (Fussel15/hSKOR1, MEIS1 and BTBD9) to two ataxias in American, European and Chinese populations - Restless Leg Syndrome and Periodic Leg Movement Syndrome." (PMID 29848623, 2018). "For example, in our cases, the Dravet syndrome patient also had a de novo variant in BTBD9 associated with the development of restless leg syndrome." (PMID 27541642, 2016). "Variants in the BTB/POZ domain-containing protein 9 gene (BTBD9) have been previously associated with restless legs syndrome (RLS)." (PMID 27708560, 2016). "Polymorphisms in BTBD9 have recently been associated with higher risk of restless legs syndrome (RLS), a neurological disorder characterized by uncomfortable sensations in the legs at rest that are relieved by movement." (PMID 22536397, 2012). "Recently, two genome-wide association studies (GWAS) have correlated polymorphisms in the BTBD9 gene with restless legs syndrome (RLS), a neurological disorder characterized by unpleasant sensations in the legs at rest that are relieved by movement." (PMID 22536397, 2012). "Regards BTBD9 C/T variant, associated with periodic limb movements in sleep (restless leg syndrome), currently individuals with C/T and TT genotypes have lower values of serum ferritin and higher levels of hepcidin and hepcidin/ferritin ratio compared with C/C genotype." (PMID 33367529, 2021). "One of the human genes associated with Restless Leg Syndrome has been validated in flies (BTBD9)." (PMID 29848623, 2018). "Genetic variation of BTBD9 was associated with susceptibility to Restless Legs Syndrome." (PMID 29228715, 2017). "Btbd9 has mostly been studied in the context of its role in Restless Legs Syndrome and the regulation of sleep by its substrates." (PMID 39273066, 2024). "Twenty seven SNPs were found to be associated with sleep start, including three SNPs at or near gene MEIS1 related to Restless Leg Syndrome and insomnia and nineteen SNPs at gene BTBD9 also related to Restless Leg Syndrome." (PMID 33075057, 2020). "Antipsychotic-induced restless legs syndrome was linked to polymorphisms located on CLOCK, BTBD9, GNB3, and TH genes, clozapine-induced somnolence was correlated with polymorphisms of HNMT gene, while insomnia was associated with variants of the MTNR1 gene." (PMID 29587340, 2018). "The lead variants at these three loci are in strong to modest LD with the previously reported variants associated with restless legs syndrome (rs113851554, MEIS1, P = 2 × 10−35, LD r2 = 1.00; rs12991815, C1D, P = 2 × 10−9, LD r2 = 0.96; rs9369062, BTBD9, P = 9 × 10−14, LD r2 = 0.49)." (PMID 30952852, 2019). "Interestingly, Cul3 has also been linked to sleep behavior via a candidate gene for Restless Leg Syndrome (RLS) and BTB gene, BTBD9." (PMID 23055946, 2012). "However, two of these variants were associated with non-neurodevelopmental disorders: a BTBD9 variant linked to restless leg syndrome, and an ATP8B1 SNV associated with familial cholestasis, respectively." (PMID 27541642, 2016). "The genes FAM120A, BTBD9, and RNF103 have not been previously linked to cancer; rather, they have been associated with schizophrenia, restless leg syndrome, and depression, respectively." (PMID 40608007, 2025).
restless legs syndrome (continued). "To understand the function of the BTBD9 protein in vivo and its potential role in the pathophysiology of restless legs syndrome (RLS), we generated a knockout of the Btbd9 gene, the mouse homolog of the human BTBD9 gene, and found that this protein is expressed in the hippocampus." (PMID 22536397, 2012).
migraine (3 papers, 2020 to 2025). "A recent genome-wide analysis revealed two novel loci associated with RLS in patients with migraine in addition to six previously identified RLS risk loci, namely, MEIS1, BTBD9 and PTPRD." (PMID 39801933, 2025). "Previous GWASs have identified six RLS risk loci (MEIS1, BTBD9, MAP2K5, PTPRD, TOX3, and an intergenic region on chromosome 2p14); however, only MEIS1 has been found to be associated with RLS in patients with migraine via candidate gene approach." (PMID 35350973, 2022).
schizophrenia (3 papers, 2018 to 2025). A major psychotic disorder characterized by abnormalities in the perception or expression of reality. "Likewise, the detection of a link between schizophrenia-related sleep disorders and genes implicated in neurotransmitter metabolism (TH and HNMT) and signal transduction (GNB3 and BTBD9) emphasizes the central role of neurotransmission disturbances in the emergence of schizophrenia symptomatology." (PMID 29587340, 2018).
lung carcinoma (2 papers, 2020 to 2021). "Moreover, the mRNA expression of BTBD9 is associated with the overall survival in lung cancer patients." (PMID 33714206, 2021). "Finally, bioinformatics and clinical sample analyses revealed that BTBD9 was downregulated while TNFAIP1 was overexpressed in human lung cancer, which was associated with poor overall survival of patients." (PMID 32327643, 2020). "Finally, we clarified that TNFAIP1 is overexpressed in the development of lung cancer due to dysfunction of CRL3 adaptor protein BTBD9, which is also associated with poor prognosis in lung cancer patients." (PMID 32327643, 2020). "An E3 ubiquitin ligase complex CRL3(BTBD9) targets TNFAIP1 for degradation to suppress lung cancer cell migration." (PMID 33714206, 2021). "To elucidate the molecular mechanism by which BTBD9 regulates TNFAIP1 to affect lung cancer cell migration, we detected the expression level of RhoA, which was reported to be regulated by TNFAIP1 and responsible for stress fiber formation." (PMID 32327643, 2020). "A Transwell assay demonstrated that the migration of lung cancer cells was elevated when BTBD9 was silenced." (PMID 32327643, 2020). "Meanwhile, prognostic analysis showed that the low mRNA expression of BTBD9 was positively correlated with poor prognosis in lung cancer patients (in lung adenocarcinoma: p = 0.007; in lung squamous cell carcinoma, p = 0.060, log-rank test)." (PMID 32327643, 2020). "Functionally, we found that BTBD9 suppressed lung cancer cell migration by promoting TNFAIP1 degradation in vitro." (PMID 32327643, 2020). "As such, downregulation of BTBD9 promoted lung cancer cell migration by upregulating the expression of TNFAIP1, whereas TNFAIP1 deletion abrogated this effect." (PMID 32327643, 2020). "Finally, as the specific adaptor of TNFAIP1, BTBD9 was found to be expressed at low levels in lung cancer, leading to the dysregulation of CRL3BTBD9 and subsequent upregulation of TNFAIP1." (PMID 32327643, 2020). "However, the silencing of neither BTBD9 nor TNFAIP1 affected cancer cell proliferation, and our study systematically demonstrated that the downregulation of BTBD9 halted TNFAIP1 degradation in lung cancer and subsequently drove lung cancer cell metastasis." (PMID 32327643, 2020). "We speculated that BTBD9 affected the expression of these proteins by modulating TNFAIP1 degradation and altering the metastatic ability of lung cancer cells." (PMID 32327643, 2020).
alcohol dependence (1 paper, 2022). Physical and psychological dependence on alcohol. "Three SNPs on Chromosome 6, rs4141854, rs9394515, and rs4711553 are all located in the BTBD9 gene, and have significant maternally derived effect on alcohol dependence, where the corresponding p-values at these three SNPs are respectively 2.797×10−11, 2.797×10−11 and 2.790×10−11." (PMID 35559008, 2022).
autism (1 paper, 2016). Persistent deficits in social interaction and communication and interaction as well as a markedly restricted repertoire of activity and interest as well as repetitive patterns of behavior. "This being the first time CNVs of BTBD9 have been identified in individuals with OCD, we expanded our analysis by also inspecting our unpublished microarray, exome, and whole-genome sequencing data in autism cases for CNVs or loss-of-function mutations in this gene." (PMID 27777633, 2016).
Dravet syndrome (1 paper, 2016). "Interestingly, the BTBD9 variant was detected in the same patient that carried the SCN1A variant associated with Dravet syndrome." (PMID 27541642, 2016).
end-stage renal disease (1 paper, 2019). "However, little is known about the relationship of BTBD9 and end-stage renal disease to RLS pathophysiology." (PMID 31704978, 2019). "Here we evaluated sleep and leg muscle activity of Btbd9 mutant (MT) mice after administration of serum from patients with either idiopathic or RLS due to end-stage renal disease (renal RLS) and investigated the efficacy of treatment with the dopamine agonist rotigotine." (PMID 31704978, 2019).
cancer (3 papers, 2012 to 2025). A tumor composed of atypical neoplastic, often pleomorphic cells that invade other tissues. "Altogether, our results suggest that BTBD9 suppresses cancer cell migration by promoting TNFAIP1 degradation." (PMID 32327643, 2020). "Moreover, BTBD9 was shown to suppress cancer cell migration by triggering TNFAIP1 degradation." (PMID 32327643, 2020). "Noteworthy, several candidate susceptibility genes (PRKCA, BMP6, ADAMTS19, ARHGAP6, FUT9/8, FAM108C1, CHL1, BTBD9 and WDR52) are involved in the actin cytoskeleton arrangement, cell adhesion and cell motility processes, which are important for cancer invasion and metastasis." (PMID 22532847, 2012). "Therefore, we speculated that BTBD9 regulated the degradation of TNFAIP1 and affected the metastasis of cancer cells in a RhoA-independent manner." (PMID 32327643, 2020).
psychiatric diseases (2 papers, 2017 to 2020). "Our earlier association studies in Polish patients with GTS have revealed a relationship between some SNPs of BTBD9, ADORA1 and ADORA2A genes and co-morbid psychiatric disorders." (PMID 32194619, 2020).
tumor (2 papers, 2018 to 2020). "Moreover, low expression of BTBD9 was associated with reduced overall survival of patients, indicating the tumor-suppressive role of BTBD9." (PMID 32327643, 2020). "Finally, cluster 4 is distinguished by a low point mutation burden (~80 coding mutations per tumor), as well as high expression of three genes (BTBD9, CDYL, TFAP2A) and high methylation at 100 promoters." (PMID 30367051, 2018).
BTBD9 also shares sentences with these, for which no sentence is quoted: insomnia (2 papers); neurodevelopmental disorder (2); sleep disorder (2); Tourette syndrome (2); adenoma (1); depression (1); gout (1); Lesch-Nyhan syndrome (1); lung adenocarcinoma (1); lung squamous cell carcinoma (1); neuroblastoma (1); neurological disorder (1); osteopetrosis (1); somnolence (1).